FANCD2 (FA complementation group D2)
Diseases named in the same sentence as FANCD2 in open-access papers (continued):
Sharing a sentence is not in itself a finding about the gene and the disease.
cancer (148 papers, 2005 to 2025). A tumor composed of atypical neoplastic, often pleomorphic cells that invade other tissues. "With regards to FANCD2, the O/E for cancer risk and more specifically BC risk, were similar to that of BRCA2 (FANCD1), an established high-risk BC gene." (PMID 38814507, 2024). "The findings demonstrated a significant association between FANCD2 expression and these two pathways across various types of cancer." (PMID 38443946, 2024). "In our study, we conducted a comprehensive pan-cancer analysis using the TIMER database to investigate the association between FANCD2 expression and the infiltration of six immune-related cell types." (PMID 38443946, 2024). "The results demonstrate that FANCD2 is significantly upregulated in various common cancers and is associated with prognosis." (PMID 38443946, 2024). "Among the 32 different cancer types examined, it was found that 11.92% of the BLCA population possessed mutations in the FANCD2 gene, representing the highest occurrence rate among all cancer types." (PMID 38443946, 2024). "The risk to mono-allelic FANCD2 carriers to develop cancer were investigated using the relatives of patients with FA enrolled in the National Cancer Institute Bone Marrow Failure Syndrome cohort." (PMID 38814507, 2024). "While only one ALT and telomerase cancer cell line were compared for telomere fragility in this study, the authors also show FANCD2 loss results in telomere hyper-extension in a BLM-dependent manner in ALT cells." (PMID 36833275, 2023). "Fanca- and Fancd2-deficient mice are models of the human disease FA with reduced frequencies of blood stem cells, increased cancer predisposition and infertility." (PMID 37580626, 2023). "Generally, cancer patients with the BRCA2 mutations were reported to have a more aggressive phenotype compared to those with FANCD2 mutation." (PMID 36686473, 2022). "The FANCD2 overexpression promotes the resistance to PARP inhibitors in BRCA1/2 deficient cancer cells." (PMID 35754466, 2022). "There is a need to further understand the involvement of DDB2, FANCG and FANCD2 with respect to cancer risk, in order to facilitate personalized medicine for the carriers." (PMID 36428697, 2022). "Collectively, these in vitro findings suggest that FANCD2-deficient cancer cells are hypersensitive to inhibition of POLQ-mediated repair." (PMID 34206946, 2021). "FANCD2 deficiency in mice confers cancer susceptibility for acute myeloid leukemia and squamous cell carcinomas." (PMID 32906798, 2020). "Elevated FANCD2 expression also increases cancer therapy tolerance and is associated with an increased risk of metastasis." (PMID 32372224, 2020). "Loss of FancD2 potentiates E7 driven cancers of the female lower reproductive tract, and head and neck in two separate studies using mouse models." (PMID 30818369, 2019). "Despite the premature senescence observed in FANCD2 depleted cells, cancer predisposition is observed in FA." (PMID 31745226, 2019). "FANCD2 also stabilizes stalled replication forks in BRCA1/2 deficient cancers, permitting their viability in extremely unstable genetic conditions." (PMID 28239445, 2017). "This indicates that not only the cancers but even some precancerous lesions must escape from their dependency on E7 in the FancD2-deficient mice." (PMID 27190216, 2016). "The association of ‘early’ FA genes with FANCD2 monoubiquitination defects with increased cancer susceptibility is much weaker compared with the ‘late’ FA genes such as BRCA1, BRCA2, BRIP1, PALB2 and RAD51C." (PMID 26085575, 2015).
cancer (continued). "In vivo, the elevation of FAVL, a tumor promotion factor that inhibits FANCD2 activation, was found to be positively associated with ΔNp63 expression in human cancer tissues." (PMID 23965832, 2013). "Our study reveals a previously unrealized role for inactivated FANCD2 in upregulating ΔNp63, contributing to the cancer susceptibility of FA as well as the tumorigenicity of an impaired FA pathway in the development of non-FA human tumors." (PMID 23965832, 2013). "Fancd2, moreover, has recently been reported to be associated with chemoresistance in cancer cells." (PMID 38218826, 2024). "Moreover, our research advances the understanding of the role of FANCD2 in cancer immunotherapy, as we have observed significant associations between FANCD2, immune cells, and immune checkpoints." (PMID 38443946, 2024). "Previous studies have linked Fancd2 to susceptibility to cancer." (PMID 38218826, 2024). "However, FANCD2 expression was repeatedly reported to be associated with poor prognosis in various cancers and to be higher in tumors than in normal tissues." (PMID 39768544, 2024). "The Kyoto Encyclopedia of Genes and Genomes (KEGG) pathway analysis indicated that aberrantly expressed FANCD2 was potentially linked with several cancer-associated signaling pathways, including chromosome segregation, DNA replication, and cell cycle transition." (PMID 35754466, 2022). "Biallelic germline mutations in FANCD2 increase cancer susceptibility." (PMID 32906798, 2020). "While ATM, BRCA, and POLQ mutations were similarly prevalent in both cancer types, adenocarcinoma patients had a high frequency to mutations effecting FANCM (8.9%) and FANCD2 (5.6%), comprising a majority of the difference between the two cancers in overall HR mutation rate." (PMID 33214570, 2020). "FANCD2 has been well-studied in regards to cancer susceptibility and initiation." (PMID 32906798, 2020). "The incidence of HPV-associated cancers was increased in FancD2-deficient mice." (PMID 27190216, 2016). "We propose a surveillance role for FANCD2 that is required to resolve replication-associated DSBs arising from any stress source and which might be relevant for the etiology of cancer in FA patients." (PMID 26765540, 2016). "Although mono-allelic disruptive variants in FANCD2 is rare, they are now more frequently identified during genetic testing, emphasizing the need for a thorough understanding of the function and epidemiology of this gene with regards to cancer and more specifically BC risk." (PMID 38814507, 2024). "Collectively, our data demonstrate that continuous cycling of SETX-deficient cells relies on FANCD2-mediated rescue of endogenous RS and chromosome under-replication during mitosis, underscoring the possibility to exploit a novel synthetic proliferation defect for cancer therapy." (PMID 36543851, 2022). "A FANCD2 p.I273V missense variant of unknown significance was the only germline mutation detected by using the 596-gene panel in this patient with family history of cancer." (PMID 32014051, 2020). "Therefore, it is very crucial to study the characteristics of FANCD2, the center player of the FA signaling network that orchestrates the unity of FA signaling in the fight against diseases associated with genome instability, such as aging and cancer." (PMID 33099537, 2020). "Mutations within the domain VI of BLM detected in human cancer samples demonstrate the functional importance of this domain, suggesting human tumorigenicity resulting from mtBLM may be at least partly attributed to mitigated FANCD2 activation." (PMID 27083049, 2016). "The deubiquitinating enzyme USP1:UAF1, a therapeutic target in cancer, normally removes ubiquitin from FANCD2 unless FANCI is also modified." (PMID 40447800, 2025). "Here, we found that repression of FANCA and FANCD2 resulted in a significant elevated effect with the LysoTracker dye retention suggesting lysosomal health also depends on FA gene function in non-cancer cells." (PMID 41188232, 2025).
cancer (continued). "The O/E for all cancer types were 2.8 for BRCA2 and 2.85 for FANCD2, with the risk for BC specifically indicated as 11.0 and 16.3, respectively." (PMID 38814507, 2024). "We observed a significant correlation between FANCD2 expression and the abundance of infiltrating immune cells in various cancer types." (PMID 38443946, 2024). "The cBioPortal online tool was employed to examine the expression status of FANCD2 across multiple cancer types." (PMID 38443946, 2024). "Firstly, although bioinformatic analyses have offered valuable insights into the role of FANCD2 in pan-cancer, it is necessary to conduct further experiments to validate these findings." (PMID 38443946, 2024). "Based on an analysis conducted using the cBioPortal database, it has been observed that alterations in the FANCD2 gene are prevalent across various types of cancer." (PMID 38443946, 2024). "In this study, we have examined the correlation between the expression of FANCD2 and the infiltration of immune-related cells, revealing a close relationship between the level of immune cell infiltration and FANCD2 expression across various cancer types." (PMID 38443946, 2024). "Recent evidence has shed light on the significant role of FANCD2 in cancer initiation, development, and progression." (PMID 38443946, 2024). "While previous investigations have delineated the carcinogenic impact of FANCD2 in diverse solid malignancies, limited knowledge exists regarding its expression and functionality in pan-cancer." (PMID 38443946, 2024). "Through this comprehensive pan-cancer analysis, we have gained a deeper understanding of the functions of FANCD2 in oncogenesis and metastasis across different types of cancer." (PMID 38443946, 2024). "Moving forward, conducting further experiments and prospective studies on FANCD2 in diverse cancer types can provide valuable insights into its regulatory mechanisms and contribute to the development of targeted therapeutic strategies." (PMID 38443946, 2024). "Mutations in the FANCD2 gene impair the interaction between the FANC protein complex and BRCA1 (breast cancer-associated 1)." (PMID 39768544, 2024). "Given the significance of pan-cancer analysis, the objective of this study was to comprehensively investigate the expression of FANCD2 across multiple cancer types." (PMID 38443946, 2024). "To validate the protein expression of FANCD2, we obtained the IHC results of FANCD2 in pan-cancer from the HPA database." (PMID 38443946, 2024). "This endeavor seeks to foster an enhanced comprehension of the latent attributes of FANCD2 in human cancers." (PMID 38443946, 2024). "We conducted Cox proportional hazards model and Kaplan-Meier analysis to investigate the prognostic value of FANCD2 across a range of cancer types." (PMID 38443946, 2024). "We investigated the expression patterns of FANCD2 in tumor tissues across various stages (I to IV) of multiple cancers using the TCGA database." (PMID 38443946, 2024). "In conclusion, our comprehensive analysis of pan-cancer data has shed light on the potential involvement of FANCD2 in a wide range of cancer types." (PMID 38443946, 2024). "In cancer cells FANCD2 usually co-localizes with mitotic EdU foci, and breaks at CFSs, so its relevance to MiDAS is not surprising." (PMID 36833275, 2023). "Here, we show that FANCD2 is necessary to counteract endogenous RS and allow proliferation of SETX-deficient cancer cells." (PMID 36543851, 2022). "In AYA BRCA we identified more frequent FANCM, FANCD2, and BRCA1 mutations when controlling for TMB, suggesting the role of DNA damage repair in this cancer type." (PMID 36433963, 2022). "In esophageal squamous cell carcinoma, depletion of FANCD2 protein suppresses cancer proliferation and metastasis by inhibiting cyclin-CDK and ATR/ATM signaling." (PMID 35754466, 2022). "Emerging evidence has indicated that FANCD2 inhibition can sensitize cancer cells to therapeutic agents." (PMID 35754466, 2022).
cancer (continued). "Our goal was to detect the potential function of FANCD2 in various TCGA cancer types and to investigate the correlation of immunotherapy between FANCD2 and HCC." (PMID 36246623, 2022). "FANCD2 can be used as a target for the development of new cancer therapies aimed at reducing the side effects of ferroptosis." (PMID 35309947, 2022). "The FANCD2 has crosstalk with RNA processing and extracellular vesicles to enhance cancer metastasis and drug resistance." (PMID 35754466, 2022). "These included the following genes known for their association with cancer: BRAF (V600E) and PIK3CA (E545K), both harboring hotspot mutations and three other possible driver genes, SDHC (H127R), DDR2 (R668C), and FANCD2 (C1130Y)." (PMID 34301805, 2021). "POLQ was revealed to be synthetic lethal with DNA repair genes frequently mutated in cancer (such as ATM, ATR, BRCA1/2, FANCD2, Ku70, RAD52, RAD51C, TP53BP1) and extensive efforts for the development of Polθ inhibitors are made by several companies." (PMID 34201502, 2021). "In addition, our studies on FANCD2 variants demonstrate an in-depth understanding of how FA signaling is timely in guarding genome stability, which may bring promising biomarkers that are useful for cancer prevention and/or earlier cancer diagnosis." (PMID 34884777, 2021). "We identified two drug targets in COAD as follows: the first one is FANCD2 (ferroptosis negative regulator, down), and it is involved in ferroptosis, a newly described cell death mechanism potentially used as cancer therapy." (PMID 33670487, 2021). "Our study also showed that FANCD1 and FANCD2 mutated to different degrees in CCA, and their expression in CCA and matched para-carcinoma tissues was also significantly different." (PMID 33472169, 2021). "Our results reveal how monoubiquitinated FANCI:FANCD2, defective in many cancer types and all cases of FA, is activated upon DNA binding." (PMID 32167469, 2020). "Of note, BLM and FANCD2 were differentially expressed between the Long TL and Short TL groups in 30% (9/30) of cancer types." (PMID 32784588, 2020). "Depletion of FANCD2 protein expression significantly suppresses the cancer cell proliferation and tumor colony formation and metastasis potential, as well as cell cycle progression, by involving specific cell signaling pathways." (PMID 32906798, 2020). "Fifty-six genes were identified as significant genes and included cancer-associated genes such as BOK, FANCD2, ADRM1 and EGLN1." (PMID 32437477, 2020). "In particular, genes known to be associated with cancer such as LAMC2, UBE2C, AKT2, AKT2, BOK, MAP4, and FANCD2 were noted to be aberrantly spliced, indicating that the aberrant expression of CPSF1 significantly altered the ASEs of oncogenes in each dataset." (PMID 32437477, 2020). "On the other hand, in some cancers, FANCD2 mono-ubiquitination has been shown to be essential for cell survival." (PMID 32409752, 2020). "Depletion of FANCD2 protein expression significantly suppresses the cancer cell proliferation and tumor colony formation and metastasis potential, as well as cell cycle progression, by involving cyclin-CDK and ATR/ATM signaling." (PMID 32906798, 2020). "In cancer cells, FANCD2 also interacts with FOXO3 to regulate antioxidant gene expression in response to oxidative stress." (PMID 32372224, 2020). "Numerous efforts have been made to develop small molecule inhibitors to modulate reversible monoubiquitination of FANCD2 and inhibit the FA pathway, thereby augmenting the sensitivity of cancer cells to cytotoxic chemotherapy regimens, including platinum." (PMID 30789902, 2019). "We found that 53BP1 forms spontaneous nuclear foci during DNA replication in both normal diploid and cancer cells, where more than half of them surround the FANCD2 foci." (PMID 29445165, 2018). "The PI3K/Akt signaling pathway also plays a key role in cancer cells’ survival in response to DNA damage by controlling FANCD2 and ribonucleotide reductase (RNR)." (PMID 28680363, 2017).
cancer (continued). "The dependence of BRCA1/2 cancers on FANCD2 in promoting Alt-EJ makes exploitation of the FA pathway an attractive option for targeted therapies." (PMID 28239445, 2017). "Collectively, our study demonstrates a novel role of FANCD2 in governing cellular ATP production, and advances our understanding of how defective FA signaling contributes to aging and cancer at the energy metabolism level." (PMID 28687786, 2017). "The severity of disease (this assesses all stages of disease from hyperplasia to cancer) in the Bi-L E7/K14–tTA/FancD2+/+ mice was significantly worse than in the FancD2+/+ mice (P = 0.008)." (PMID 27190216, 2016). "H1299 FANCD2 knock-down cancer cells were also more sensitive to BMN673 compared to empty vectors transfected control cells (25 vs. 62% viable cells, respectively) 72 h post treatment." (PMID 25566506, 2014). "Recent advances in cancer biology have demonstrated that PI3K-AKT-mTOR signaling pathway controls Fanconi anemia group D2 protein (FANCD2) and ribonucleotide reductase (RNR) and further prolongation of radiation-induced gamma H2AX foci formation." (PMID 25988165, 2014). "Since FANCD2 foci formation is critical for cancer cells to resist MMC and cisplatin, the best way to assess the functionality of this repair pathway as a whole is by evaluating FANCD2 foci formation." (PMID 25566506, 2014). "Much effort has been made to understand the roles that FANCD2 plays upon DNA damage and in the subsequent suppression of the development of human cancer." (PMID 24658369, 2014). "Collectively, these results document a novel role of an inactivated FANCD2 in upregulating ΔNp63, advancing our understanding of how an impaired FA pathway contributes to the pathogenesis of human cancer." (PMID 23965832, 2013). "The next closest Alu to a deletion-prone cancer gene exon occurs at exon 19 of FANCD2 with a separation of 20 bp." (PMID 23755193, 2013). "Cigarette smoke condensate suppressed FANCD2 in cancer cells, but these cells were significantly more resistant to CSC in survival and apoptosis assays than were normal airway epithelial cells." (PMID 18475298, 2008). "Additionally, we have observed a decrease in the methylation of FANCD2 DNA in some cancers, and this decrease is inversely correlated with FANCD2 expression." (PMID 38443946, 2024). "Furthermore, a comprehensive assessment was carried out to investigate the relationship between FANCD2 expression levels and disease-specific survival or progression-free intervals in cancer patients." (PMID 38443946, 2024). "In addition, FANCD2 expression was positively correlated with the DDR pathway in 28 cancers, except CHOL, KIRC, THCA, UCS, and UVM." (PMID 38443946, 2024). "Additionally, we observed a significant increase in FANCD2 expression with the progression of the disease in the majority of analyzed cancers." (PMID 38443946, 2024). "Flaws in FANCD2 result in a rise in genetic material harm and the formation of cancer." (PMID 39400935, 2024). "By amalgamating these findings, we posit that FANCD2 could serve as a novel and efficacious target for anti-cancer immunotherapy, complementing the use of chemotherapeutic agents." (PMID 38443946, 2024).